INS (insulin)
Diseases named in the same sentence as INS in open-access papers (continued):
Sharing a sentence is not in itself a finding about the gene and the disease.
Hyperglycemia (continued). "In this study, we investigated the effects of STZ-induced hyperglycemia on development and progression of NAFLD in hamsters, as well as the effects of insulin treatment on liver pathology and hepatic gene expression in a dyslipidemic, hyperglycemic setting." (PMID 33596938, 2021). "Of particular note, hyperglycemia-induced oxidative stress also activates JNK, an upstream transcription factor in the insulin resistance signal." (PMID 34685668, 2021). "TXNIP expression remains elevated as long as hyperglycemia persists, while insulin and insulin-like growth factor 1 (IGF-1) reduce TXNIP expression, however, it lasts for a few hours only if hyperglycemia persists." (PMID 34940029, 2021). "What remains is a prolonged hyperglycaemia after ingestion of nutritional fat that requires a prolonged monitoring (e.g., CGM) and prolonged dispense of insulin." (PMID 34684559, 2021). "Simultaneously, UC-MSC infusion significantly ameliorated hyperglycemia in T2DM rats and decreased inflammatory activity, which resulted in improved insulin sensitivity in insulin target tissues." (PMID 34135959, 2021). "This pilot, randomized, open-label controlled study compared the basal–bolus regimens of insulin glargine (IG) and neutral protamine Hagedorn (NPH) insulin in stroke patients with hyperglycemia receiving intensive care." (PMID 34075142, 2021). "While GLP-1 agonists stimulate insulin secretion and suppress glucagon production, SGLT-2-inhibitors improve hyperglycemia by enhanced glucosuria." (PMID 33808404, 2021). "Taken together, these results indicate that Ipra reduces UAE as well as hyperglycemia in HFD-fed mice, and that Ipra increases lipogenesis and lipolysis capacity while enhancing insulin signaling in PRAT of HFD-fed mice." (PMID 34298949, 2021). "Chronic hyperglycemia abolishes the ability of glucose to enhance release of glutamate from afferent terminals in the NTS, and type 1 diabetic rats and insulin-resistant, hyperglycemic male OZRs develop diminished baroreflex-mediated activation of the NTS." (PMID 33978481, 2021). "Importantly, in most of these patients no major changes in hormones were detected and hyperglycemia resolved after partial nephrectomy allowing discontinuation of insulin therapy and thus suggesting that onset of hyperglycemia could have been metabolic in nature." (PMID 34822425, 2021). "Additionally, an association between insulin and inflammation was observed in populations with T2DM and hyperglycemia.The mechanism by which hyperinsulinemia promotes inflammation is not clearly defined but may be related to its positive effect on body weight and visceral adiposity." (PMID 33691751, 2021). "It is possible that lesogaberan helped to correct hyperglycemia by acting on islet β-cell or α-cell GABAB-Rs and modulating insulin and/or glucagon release." (PMID 33418884, 2021). "The first/early phase of insulin secretion is critical in maintaining the PPG homeostasis, and can prevent chronic postprandial hyperglycemia." (PMID 34071359, 2021). "Hyperglycemia induced by chronic AVP infusion was diminished by concomitant treatment with V1a receptor antagonist, whereas, insulin levels were the same as the group that had normal AVP concentration." (PMID 33905792, 2021). "Concomitant with hyperglycemia, mice fed HFD display increased plasma insulin due to increased insulin demand." (PMID 33239359, 2021). "Although encouraging, protocols for insulin and CHO adaptation still require refinement to significantly reduce episodes of hypo- and hyperglycemia in children practicing sports, especially when under MDI regimen." (PMID 34512541, 2021). "In fact, the HSuHF-fed rats presented postprandial hyperglycemia, glucose intolerance (as viewed by the GTT), postprandial hyperinsulinemia, and reduced insulin sensitivity (as suggested by the ITT), as well as hypertriglyceridemia." (PMID 34959746, 2021).
Hyperglycemia (continued). "In mice with hyperglycemia induced by a high-fat diet, BBR significantly increases insulin secretion and reduced blood glucose levels." (PMID 34556670, 2021). "Despite normal levels of circulating insulin in LFD Inpp4b−/− males, the rate of hepatic gluconeogenesis was increased, confirming that lean knockout males developed hyperglycemia." (PMID 33772116, 2021). "According to glucose metabolism, leptin has been long related to glucose homeostasis improving insulin sensitivity, since intra-VMH injection of leptin increases glucose uptake in peripheral tissues and normalizes hyperglycemia." (PMID 34201257, 2021). "Hyperglycemia is most commonly seen with PI3K-α inhibition (selective and pan-inhibitors), due to therapy induced disruptions in insulin signaling and glucose hemostasis leading to clinically evident metabolic changes." (PMID 34512641, 2021). "Mice with liver-specific double IRS1 and IRS2 knockout exhibit severe hyperglycemia, suggesting that liver IRS1 and IRS2 are the critical mediators of insulin’s regulation of glucose metabolism." (PMID 33672754, 2021). "It is shown that GPR119 agonists reduce hyperglycemia by stimulating intestinal GLP-1 secretion, improving pancreatic β-cell function and insulin secretion." (PMID 34884651, 2021). "Thus, the data indicate that the reduction in insulin is not due to increased β-cell death but rather due to the loss of β-cell identity, which may in part be exacerbated by hyperglycemia itself." (PMID 34487921, 2021). "In contrast, during clamped hyperglycemia, OLE infusion resulted in a significant decrease in insulin clearance, compared with SAL infusion." (PMID 34948019, 2021). "OLETF group with hyperglycemia showed an increase in HbA1c, serum TNF‐α, and muscle SERCA activity, but a decrease in circulating insulin." (PMID 34558206, 2021). "Probably, the observed hyperglycemia can be also attributed to impaired uptake of GLU from skeletal muscle and liver and in general all INS-dependent tissues." (PMID 33744871, 2021). "Administration of the protein preload markedly reduced postprandial hyperglycemia and increased plasma GIP and insulin levels whereas increased GLP-1 secretion after the carbohydrate meal." (PMID 33419065, 2021). "This situation was maintained from 14 to 26 weeks of age, and LRGT helped to increase insulin levels in the diabetic mice (db/db-LRGT and APP/PS1xb/db-LRGT) to control hyperglycemia." (PMID 34975451, 2021). "This suppresses the down-stream signaling of IRS1 tyrosine phosphorylation, PDK1 activation, and AKT phosphorylation, resulting in insulin-dependent glucose uptake and translocation of GLUT4 inhibition, and ultimately results in hyperglycemia." (PMID 34681689, 2021). "However, a recent trial suggested that for patients with acute ischemic stroke and hyperglycemia, aggressive intravenous insulin infusion has a significantly higher chance of inducing hypoglycemia without absolute clinical benefits compared with subcutaneous insulin injection." (PMID 34075142, 2021). "Consistently, in insulin-resistant Albino Wistar rats, a GSP diet (100 mg/kg) improves hyperglycemia and hyperinsulinemia, increasing tyrosine phosphorylation of IR-β and IRS-1 and decreased serine phosphorylation of IRS-1." (PMID 34439477, 2021). "However, the novelty aspect in this study is that the determination of morin effects on bone histomorphometry along with the suggestion of insulin/IGF-1 as another protective pathway by which morin might protect skeletal tissues from the deleterious effects of hyperglycemia." (PMID 34371877, 2021). "Consistent with previous studies, HIP rats had glucose intolerance, with both impaired glucose stimulated insulin secretion apparent from the attenuated C-peptide response (~twofold decrease in peak C-peptide in HIP vs. WT, P < 0.05) despite hyperglycemia." (PMID 34012065, 2021).
Hyperglycemia (continued). "Under conditions of hyperglycemia and perturbed GSIS, the glucose transporter Slc2a2 is markedly downregulated, which correlates with an impaired insulin secretory response in both mice and rats." (PMID 34949756, 2021). "The plant extract provoked an inhibition of hyperglycemia during OGTT and a significant increase in the insulin sensitivity index." (PMID 34204042, 2021). "The liver is a key organ to glucose homeostasis since insulin resistance in this organ increases hepatic glucose production (HGP) and fasting hyperglycemia." (PMID 34203825, 2021). "In response to insulin, enterocytes internalize GLUT2 from the basolateral site of enterocytes in order to prevent further transport of glucose in the blood during hyperglycemia." (PMID 33435513, 2021). "Contrary to the enhanced activity of PDX1 upon acute glucose increase, chronic exposure to hyperglycemia resulted in the downregulation of PDX1 mRNA and protein in HIT-15 cells, an insulin reporter-expressing cell line derived from hamster islet cells." (PMID 32394191, 2020). "This electronic device then communicates with the insulin pump and CGM to perform actions, such as the application of insulin or issuing warnings via a smartphone for hypoglycemia or hyperglycemia." (PMID 33332410, 2020). "Additionally, there has been growing emphasis in the literature on women with gestational diabetes under medical nutrition therapy or, in some cases, with apparent normal glucose metabolism, where—nevertheless—hyperglycemia may occur, necessitating the initiation of transient insulin therapy." (PMID 32079162, 2020). "In the present investigation, DC rats showed decreased insulin levels and elevated FBG and HbA1c levels, which are characteristics of hyperglycemia." (PMID 33187275, 2020). "Hence, we suggest a careful and slower rate of hyperglycemia correction, considering the glucose-lowering effect of dialysis and/or potentially avoiding the use of intravenous insulin bolus on starting the insulin infusion, which may decrease the risk of hypoglycemia." (PMID 32111715, 2020). "Taken together we concluded that the onset of aging isassociated with hyperinsulinemia, moderate hyperglycemia and diminished GGT, while advancedaging is accomplished with reduction of insulin production along with elevated glucoseconcentration." (PMID 32779434, 2020). "Cowley's group observed, in a recent study of DIO mice, that leptin signaling in ARC neurons (most likely AgRP neurons) blocked the suppressing effect of insulin on hepatic glucose production through upregulation of PTP1B, leading to hyperglycemia." (PMID 32731387, 2020). "Hyperglycemia develops as a result of an impairment in glucose uptake into skeletal muscle and WAT, secondary to a defect in the action of insulin, the key regulator of glucose homeostasis." (PMID 32041272, 2020). "The loss of FXR signalling impairs hepatic glucose homeostasis and decreases insulin sensitivity, while FXR activation improves hyperglycaemia and hyperlipidaemia in diabetic mice." (PMID 33029898, 2020). "Propranolol improved postischemic hyperglycemia by subsiding oxidative stress and TNF-α-impaired insulin action in the gastrocnemius muscles." (PMID 32492962, 2020). "Some observations indicate that hyperglycemia directly downregulates GIP receptors in beta cells, disturbing late-stage insulin release." (PMID 32069846, 2020). "This is probably because the practitioners in the ICU attached more importance to avoiding hyperglycemia, and the ICU patients were mainly treated with intravenous insulin, which was easy to adjust for better BG control." (PMID 33224911, 2020). "Injection of insulin into mice expressing an albumin promoter-driven dominant negative MET receptor results in hyperglycemia, reduced insulin sensitivity and glucose clearance, suggesting that a MET is required for a normal insulin response by the liver." (PMID 32372975, 2020).
Hyperglycemia (continued). "Eventually, fully phosphorylated Akt downstream of the insulin signaling pathway in turn moderates activation by ABA of AMPK and starts the metabolic response to hyperglycemia, which includes lipid synthesis and storage." (PMID 31996711, 2020). "These β-like cells rapidly reversed hyperglycemia in STZ-diabetic mice by secreting C-peptide and insulin." (PMID 32641151, 2020). "In all of our studies, therefore, NPC43 acted as a novel insulin mimetic in the liver to directly activate INSR signaling, thereby inhibiting glucose production and enhancing glucose uptake to mitigate hyperglycemia and glucose intolerance." (PMID 31378829, 2020). "Neonatal hyperglycaemia (NNH) and its relationship with serum insulin in ill neonates is largely understudied especially in the West African sub-region." (PMID 32637004, 2020). "STZ enters the cytoplasm of β-cells in the pancreas via glucose transporter-2 and reduces insulin secretion through cell toxicity and thus, the STZ-injected animals develop hyperglycemia, resembling the conditions seen in type I diabetes." (PMID 32832559, 2020). "Regardless of the mechanism behind how cytokines, elevated FFA and hyperglycemia activate JNK, this presents a potential therapeutic target to restore insulin sensitivity and preserve β-cell function." (PMID 32183037, 2020). "Insulin and GLP-1 are the only two peptide hormones known so far to stimulate tissue glucose uptake under conditions of hyperglycemia, and GLP-1 acts by stimulating insulin release." (PMID 32526875, 2020). "The mechanism of hyperglycaemia is a combination of anti-ADH (antidiuretic hormone) effects and alterations in insulin sensitivity, resulting in an osmotic diuresis." (PMID 32570809, 2020). "Moreover, hyperglycemia increased ROS production by driving mitochondria toward increased oxygen use and decreased ATP formation, which in turn suppressed insulin generation in pancreatic β-cells by inhibiting insulin gene transcription factors such as Pdx1 or MafA63,64." (PMID 32439909, 2020). "Several clinical trials have aimed to treat hyperglycemia after TBI by glucose control via IV administration of insulin, but results have been mixed, and insulin’s ability to penetrate into the CNS during these studies is rarely considered." (PMID 33100956, 2020). "However, we should pay careful attention to the accuracy of HOMA-IR, as it might be decreased in advanced diabetic patients because hyperglycemia induces the inadequate secretion of insulin and the homeostasis between fasting glucose and insulin levels is disrupted in these patients." (PMID 30704150, 2019). "Our present findings provide a new possibility that the procyanidin-induced promotion of GLUT4 translocation, which is involved in the prevention of hyperglycaemia, is due to the activation of both the GLP-1-activated insulin-signalling and AMPK pathways." (PMID 30719284, 2019). "In diabetic db/db mice, the observed hyperglycemia and markedly impaired glucose response during the GTT were related to the diminished rate of insulin-dependent glucose uptake in the heart, muscle and adipose tissues." (PMID 31920980, 2019). "Our personalised insulin calculator is safe and effective for the correction of hyperglycaemia prior to FDG PET/CT, with markedly fewer hypoglycaemic events and significantly reduced time between insulin and FDG administration compared to an empiric protocol." (PMID 30737563, 2019). "Hyperglycemia and hypoinsulinemia were present in the 60-week-old OLETF rats, and the plasma glucose, TG, Cho, and insulin concentrations were 271 ± 5 mg/dL, 358 ± 13 mg/dL, 269 ± 14 mg/dL, and 59 ± 3 ng/dL, respectively (mean ± S.E.; n = 3)." (PMID 31614552, 2019). "Hyperglycemia elicits an increase in different cytokines, such as TNF-α, IL-1β and IL-6, whilst insulin exerts the opposite effects." (PMID 31817857, 2019).
Hyperglycemia (continued). "In a Japanese study, although they stated that hyperglycemia was observed in many patients with ACS, they emphasized that administrating insulin requires more researches." (PMID 31432036, 2019). "Furthermore, it is now well-established that adding insulin therapy in an effort to decrease hyperglycemia and prevent retinopathy, neuropathy, and nephropathy will likely exacerbate weight gain and may discourage youth from actively engaging in lifestyle management." (PMID 31736876, 2019). "In normal pregnancies, the pancreatic beta cells produce higher levels of insulin which prevents hyperglycemia, whereas, in GDM, the response of these beta cells is inadequate, leading to hyperglycemia." (PMID 31109059, 2019). "In summary, this study showed that in rats under metabolic syndrome induction, kernel oil of WP decreased hyperglycemia and HOMA-IR index and improved insulin secretion." (PMID 34466477, 2019). "The insulin secretion response to glucose was attenuated in the hypoglycemic range and it was expected that the decrease in glucagon due to GLP-1 seen in hyperglycemia would disappear." (PMID 31781045, 2019). "Insulin targets insulin‐sensitive organs, like the liver, muscle, WAT, and brain to induce glucose utilization and storage thus preventing hyperglycemia." (PMID 31423716, 2019). "Hyperglycemia in HFD/STZ diabetic rats resulted from STZ-induced destruction of the pancreatic β-cells, diminished insulin secretion and sensitivity, reduced peripheral glucose uptake, and increased hepatic glucose production." (PMID 30915195, 2019). "This can be advantageous in blocking compensatory INSR-A signaling but also problematic in compromising metabolic insulin signaling via INSR-B, leading to hyperinsulinemia and dose-limiting hyperglycemia." (PMID 31416218, 2019). "The cardiac SGLT1 is thought to be activated by various factors, such as insulin, AMP-activated protein kinase (AMPK), persistent hyperglycemia, as well as ischemia–reperfusion injury per se, all of which can also activate GLUT4." (PMID 31262297, 2019). "Thus, some functional foods, through the bioactive compounds they contain, could affect carbohydrate metabolism, giving rise to less marked postprandial hyperglycemia, improved pancreatic β-cell function and insulin secretion, as well as decreased insulin resistance." (PMID 30717491, 2019). "Hyperglycemia or hyperinsulinemia can also enhance cell–surface TGF-β receptor expression through the PI3K-Akt pathway, suggesting the possible presence of an insulin-induced autocrine TGF-β signaling pathway." (PMID 31133649, 2019). "ANP partially blocked the effect of insulin and LDL in adipocytes, but it was more effective in culture conditions simulating hyperglycemia." (PMID 30634533, 2019). "Similar to humans, preterm baboons have greater than 90% incidence of developing hyperglycemia spontaneously, have downregulation of GLUT4 shortly after birth, and exhibit decreased peripheral insulin sensitivity two weeks after birth." (PMID 30540820, 2018). "Treatment with resveratrol and 17β-estradiol prevented STZ-induced hyperglycemia, inhibited MAPK/ERK signal pathway and stimulated insulin secretion." (PMID 30273360, 2018). "In fact, an HCLS, which was used in the majority of the studies, requires a pre-meal insulin bolus by the patient, usually with the need for CHO counting to avoid postprandial hyperglycaemia." (PMID 29954380, 2018). "In support of the role of HMGA1 in INSR gene transcription, in vitro investigations in beta-pancreatic cells demonstrated that sustained hyperglycemia impaired HMGA1 expression, a condition affecting INSR content in beta cells and, thus, insulin secretion." (PMID 30034366, 2018). "Investigating in fasted Ambra1 mice the metabolic parameters correlated to clinical diagnosis of prediabetes, we found slight hyperglycemia, intolerance to glucose (GTT), insulin resistance (high insulin basal levels and ITT impairment) and hyperglucagonemia." (PMID 30532260, 2018).